DLL1 (delta like canonical Notch ligand 1)
Diseases named in the same sentence as DLL1 in open-access papers (continued):
Sharing a sentence is not in itself a finding about the gene and the disease.
infection (19 papers, 2011 to 2026). The state of being infected such as from the introduction of a foreign agent such as serum, vaccine, antigenic substance or organism. "We provided evidence that DLL1-activated Notch signaling, as occurring in severe infections, is associated with the loss of vEC barrier function." (PMID 34955884, 2021). "Patients with autoinflammatory diseases (HS, IBD) showed significantly lower DLL1 levels than patients with infection." (PMID 37298115, 2023). "Patients with a bacterial infection showed significantly elevated plasma levels of DLL1 at the timepoint before the microbial proof of infection and on the two timepoints after diagnosis." (PMID 33142943, 2020). "We recently found an upregulation of DLL1 in primary human monocytes in response to in vitro infection with various bacteria." (PMID 31396491, 2019). "Proliferation was comparable at 8 days after infection, whereas the proliferation was less in Dll1−/− than control mice 37 days after infection." (PMID 27659682, 2016). "The results showed significantly higher virus load in the lungs of mice that received anti-Dll1 Ab compared to controls at day 7 post-infection." (PMID 22072963, 2011). "In agreement with the chemokine and cytokine profile from whole lungs, flow cytometry demonstrated enhanced macrophage and neutrophil recruitment during H1N1 infection in anti-Dll1-treated mice at day 7 post-infection." (PMID 22072963, 2011). "Here, we show that stable nucleic-acid-lipid particles carrying mature miR-34a can target Dll1 in vitro and show equal effects to those of adenovirus miR-34a cell infection." (PMID 21931765, 2011). "Macrophages are indispensable for the protection against influenza virus by their enhancement of Dll1 expression levels during infection." (PMID 22072963, 2011). "Only recent findings indicated a role for DLL1 in the pathophysiology of infections." (PMID 37298115, 2023). "However, patients with infections had significantly higher DLL1 levels than patients with inflammatory diseases." (PMID 37298115, 2023). "Therefore, JAG-1-shRNA2, JAG-2-shRNA4, and DLL-1-shRNA3 vectors were chosen for subsequent stable infection." (PMID 34940631, 2021). "Interestingly, the protein level of IFN-β was significantly higher while that of IFN-γ was significantly lower in H1N1-infected whole lungs from anti-Dll1-treated mice compared to lungs from control mice 7 days post-infection." (PMID 22072963, 2011). "We also examined the expression of Dll1 from lung macrophages (CD11b+F4/80+) at Day 7 post-infection to demonstrate whether the Dll1 antibody has an inhibitory effect in vivo." (PMID 22072963, 2011). "Additionally, whole lungs from anti-Dll1 Ab treated mice at day 7 post-infection had significantly higher protein levels of CCL2 and CXCL1, molecules that play a critical role in the recruitment of monocytes/macrophges and neutrophils into inflammatory lesions." (PMID 22072963, 2011). "We found a significant increase in DLL1 expression in H. pylori-infected mice compared to uninfected (p=0.0253) control mice, and a decrease in DLL1 expression in gastric tissues from mice treated with the antibiotic eradication therapy at 8 and 22 weeks post infection (p<0.05)." (PMID 22249198, 2011). "Twenty-four hours after TLR activation through in vitro infection or LPS stimulation, the expression of JAG1 decreases, whereas DLL1 gene expression is highly induced and translated into the protein DLL1." (PMID 30042932, 2018). "The mRNA expression of Notch1, DLL1 and Hes1 were significantly higher in patients with moderate/severe TB compared to those with mild TB or no infection." (PMID 37063841, 2023). "Still, the role of DLL1-induced Notch signaling in vascular leakage during infection is not investigated." (PMID 34955884, 2021). "Patients with bacterial infection showed increased DLL1 levels compared to patients without infection." (PMID 33142943, 2020).
infection (continued). "Here we show that TLR signaling, triggered through LPS stimulation or in vitro infection with various Gram-negative and -positive bacteria, stimulates Notch receptor ligand Delta-like 1 (DLL1) expression and Notch signaling in human blood-derived monocytes." (PMID 30042932, 2018). "Our data show that LPS-stimulation and in vitro infection with Gram-negative and Gram-positive bacteria stimulates expression of Notch receptor ligand DLL1 and induction of Notch target genes in primary human monocytes." (PMID 30042932, 2018). "Notably, the DLL1 level was not an independent predictor of mortality in this population with concurrent infection." (PMID 42221134, 2026).
bacterial infection (8 papers, 2018 to 2026). "In conclusion, our results suggest that during bacterial infection and LPS recognition, DLL1-activated Notch signaling is associated with vascular permeability." (PMID 34955884, 2021). "Therefore, plasmatic measurements of DLL1 may help the clinician to identify patients with an increased risk for bacterial infections, especially within the first 7 days following LTX." (PMID 33142943, 2020). "In vitro bacterial infection led to an upregulation of DLL1 on the surface of primary human monocytes." (PMID 37298115, 2023). "Soluble DLL1 is a promising new biomarker, produced among other sources by monocytes in response to bacterial infection." (PMID 37298115, 2023). "An increase in DLL1 by DSV is supported by the findings that DLL1 is upregulated in monocytes during bacterial infection." (PMID 34336718, 2021). "In various bacterial infection models, IL-6 was reported to induce DLL-1 expression in monocytes through the activation of STAT3." (PMID 32635645, 2020). "Of interest, median concentrations of DLL1 in the subgroup with a complicated course were higher than those of the subgroup of patients with bacterial infections." (PMID 33142943, 2020). "Within this secondary analysis of a prospective clinical investigation in liver transplanted patients, DLL1 was shown to be a useful option for the detection of bacterial infections in patients following LTX, especially in combination with CRP and PCT." (PMID 33142943, 2020). "For bacterial infection, we propose for the first time a dependency of DLL1 transcription on STAT3 that is activated through TLR-induced cytokines and autocrine cytokine receptor signaling." (PMID 30042932, 2018). "From a technical perspective, to prove DLL1's potential as a biomarker of bacterial infection (and other pathologic conditions), several aspects need to be ensured: First, a standardized assay needs to be developed and used for quantification, enabling definite cut-off determination." (PMID 31396491, 2019). "Therefore, the aims of this secondary analysis are to evaluate the performance of DLL1 to diagnose bacterial infection as well as to predict a complicated clinical course of patients following liver transplantation compared to standard biomarkers such as PCT or CRP." (PMID 33142943, 2020). "Plasma levels of DLL1 following LTX may be useful to support an earlier detection of bacterial infections in combination with C-reactive protein (CRP) and procalcitonin (PCT), or they may lead to risk stratification of patients as a single marker for post-operative complications." (PMID 33142943, 2020). "Besides diagnosis of bacterial infection, elevated levels of DLL1 following LTX may be an indicator for a complicated course within 28 days or death within 90 after LTX." (PMID 33142943, 2020). "Compared to routine laboratory markers, especially to PCT, DLL1 exhibits a superior accuracy for diagnosis, but not for prognosis, of bacterial infection." (PMID 31396491, 2019). "Nevertheless, one important conclusion can be drawn from this study, despite in need of clarification in the blood: chronic HIV infection does not seem to elevate DLL1 levels per se, but only when bacterial infection occurs in addition." (PMID 31396491, 2019).
neurodevelopmental disorder (4 papers, 2022 to 2023). A behavioral and cognitive disorder with onset during the developmental period that involves impaired or aberrant development of intellectual, motor, or social functions. "To date, 38 disease-causing mutations have been identified in the DLL1 gene associated with different disorders such as neurodevelopmental disorder, autism, hearing loss, congenital heart disease, and cleft lip/or palate." (PMID 36506336, 2022). "Functional studies demonstrated that DLL1 missense variants resulted in gain-of-function effects, whereas a DLL1 variant reportedly associated with a neurodevelopmental disorder was proven to be associated with the LoF effect." (PMID 34519870, 2022). "Pathogenic DLL1 variants linked to the neurodevelopmental disorder were predicted to exhibit the LoF effect; indeed, the DLL1 p.C179F (M4) variant was trapped intracellularly, which revealed the presence of a trafficking defect." (PMID 34519870, 2022). "Among the genes in the duplicated region of our proband, the DLL1 (MIM *606,582) gene is involved in neurodevelopmental disorders with nonspecific brain abnormalities in the trisomy 6q region." (PMID 37993819, 2023).
infectious disease (3 papers, 2021 to 2024). A disorder directly resulting from the presence and activity of a microbial, viral, or parasitic agent in humans. "In infectious disease controls, a similar pattern was observed, but without correlations between DLL1 and MIF and IL-10." (PMID 38502427, 2024).
cardiovascular disease (1 paper, 2025). "For instance, strong inflammation and cardiovascular disease lead to an upregulation of ADAM metalloproteases (A Disintegrin and Metalloproteinase, ADAM10/17), which cleave membrane-bound DLL1." (PMID 40775336, 2025).
genetic diseases (1 paper, 2022). "Based on our functional study results, individuals born with germline missense gain-of-function variants in DLL1 may not exhibit defects as severe as those with other genetic diseases, owing to LoF variants in genes involved in Notch signaling." (PMID 34519870, 2022).
gynecologic tumors (1 paper, 2025). "Notably, reduced DLL1 and HES1 expression was also detected in HGSOC when compared to other (non-type II) gynecologic tumors (FC = 1.17 and 1.43, respectively; p < 0.02)." (PMID 40002854, 2025).
DLL1 also shares sentences with these, for which no sentence is quoted: renal cell carcinoma (3 papers); autism (2); Bacterial Sepsis (2); COVID-19 (2); cyst (2); inflammation (2); inflammatory bowel disease (2); Parkinson disease (2); pituitary tumor (2); prostate carcinoma (2); type 2 diabetes (2); acute liver failure (1); acute lung injury (1); acute myeloid leukemia (1); acute myocardial infarction (1); allergic rhinitis (1); anal atresia (1); autoimmune disease (1); B-cell non-Hodgkin lymphoma (1); bacterial meningitis (1); benign gynecologic tumors (1); brain cancer (1); brain malformations (1); breast adenocarcinoma (1); Burkitt lymphoma (1); cerebral autosomal dominant arteriopathy with subcortical infarcts and leukoencephalopathy (1); Cerebral ischemia (1); chronic liver failure (1); chronic obstructive pulmonary disease (1); chronic periodontitis (1).
A further 36 diseases each share a sentence with DLL1 in 1 paper.